SNORD115-4 (small nucleolar RNA, C/D box 115-4)
Synonyms: HBII-52-4
Gene: Small nucleolar RNA gene on chromosome 15 (25,176,832 to 25,176,913, forward strand). Ensembl gene ENSG00000200680.
Gene Ontology:
Biological process: RNA processing
Cellular component: nucleolus
Homologues: Orthologues: chimpanzee SNORD115 (100% identical), macaque SNORD115 (100% identical). Paralogues in human: SNORD115-42 (99% identical), SNORD115-12 (98% identical), SNORD115-15 (98% identical), SNORD115-6 (98% identical), SNORD115-9 (98% identical), SNORD115-10 (96% identical), SNORD115-11 (96% identical), SNORD115-13 (96% identical), SNORD115-14 (96% identical), SNORD115-20 (96% identical), SNORD115-29 (96% identical), SNORD115-34 (96% identical), and 37 more.